AGR2 (anterior gradient 2, protein disulphide isomerase family member)
Diseases named in the same sentence as AGR2 in open-access papers (continued):
Sharing a sentence is not in itself a finding about the gene and the disease.
ampulla of vater cancer (1 paper, 2014). A primary or metastatic malignant neoplasm involving the ampulla of Vater. "In addition, tumor-promoting activity of AGR2 was examined by knockdown of AGR2 expression with shRNA and its overexpression in AGR2-positive SNU-478 and AGR2-negative SNU-869 ampulla of Vater cancer cell lines, respectively." (PMID 25367337, 2014).
atypical endometrial hyperplasia (1 paper, 2018). An endometrial hyperplasia characterized by cytologic and architectural changes which may lead to endometrial carcinoma. "In this study, changes in the levels of endometrial AGR2 protein/AGR2 mRNA expression are shown for the first time across the normal pre and postmenopausal endometrium, premalignant atypical endometrial hyperplasia, EC and in matched metastatic lesions." (PMID 30140383, 2018).
bladder tumors (1 paper, 2016). "The microarray result of sorted CD9+ cancer cells from one bladder tumor specimen showed no AGR2 expression, but showed CD10 expression." (PMID 26894971, 2016).
cervical squamous cell carcinoma (1 paper, 2025). A squamous cell carcinoma arising from the cervical epithelium. "Within a cohort of 106 patients diagnosed with squamous cell carcinoma of the cervix, 39 cases (39/106, 36.8%) exhibited positive AGR2 expression, while 20 cases (20/106, 18.9%) displayed positivity in the corresponding adjacent non-tumor tissues (P < .05)." (PMID 41239615, 2025). "The impact of KAI1, MACC1, and AGR2 gene expression on postoperative survival rates among patients with cervical squamous cell carcinoma was assessed using the Kaplan–Meier method for univariate survival analysis." (PMID 41239615, 2025). "Expression of AGR2 in cervical squamous cell carcinoma and its correlation with clinicopathological factors." (PMID 41239615, 2025). "However, investigations into the expression levels of KAI1, MACC1, and AGR2 in cervical squamous cell carcinoma, the interrelations among these biomarkers, and their associations with clinicopathological factors remain sparse." (PMID 41239615, 2025). "Correlations between KAI1, MACC1, and AGR2 expression in cervical squamous cell carcinoma." (PMID 41239615, 2025). "Despite their individual associations with metastasis and prognosis across different cancer types, the interactions among MACC1, AGR2, and KAI1 specifically in cervical squamous cell carcinoma remain poorly understood." (PMID 41239615, 2025). "In cervical squamous cell carcinoma, the detection rates of MACC1 and AGR2 were found to be significantly elevated, whereas the detection rate of KAI1 was notably reduced when compared to control tissues." (PMID 41239615, 2025). "Immunohistochemistry was used to detect the expression of MACC1, AGR2, and KAI1 in 106 cases of cervical squamous cell carcinoma." (PMID 41239615, 2025). "In line with findings regarding MACC1, patients diagnosed with AGR2-positive squamous cell carcinoma of the cervix exhibited significantly shorter OS times than those with AGR2-negative tumors." (PMID 41239615, 2025). "MACC1, AGR2, and KAI1 may represent potential metastatic and prognostic biomarkers, as well as promising therapeutic targets for squamous cell carcinoma of the cervix." (PMID 41239615, 2025). "In this investigation, a multivariate COX regression survival analysis revealed that the positive expression of KAI1, MACC1, and AGR2, along with TNM stage and LNM stage, are independent prognostic indicators for survival in individuals diagnosed with cervical squamous cell carcinoma." (PMID 41239615, 2025). "Therefore, this study aimed to investigate the relationships between MACC1, AGR2, and KAI1 within the context of cervical squamous cell carcinoma, while also examining their correlations with clinicopathological features and overall survival (OS) outcomes in affected patients." (PMID 41239615, 2025). "Additionally, multivariate analysis indicated that the positive expression of MACC1, AGR2, and KAI1, alongside tumor stage and LNM stage, could serve as independent prognostic indicators for OS in individuals diagnosed with cervical squamous cell carcinoma." (PMID 41239615, 2025).
chronic myelogenous leukemia (1 paper, 2019). "Down-regulation of miR-217 was associated with over-expression of AGR2 in chronic myelogenous leukemia cells." (PMID 30665445, 2019).
Cirrhosis (1 paper, 2023). A chronic disorder of the liver in which liver tissue becomes scarred and is partially replaced by regenerative nodules and fibrotic tissue resulting in loss of liver function. "Multivariate analysis showed that cirrhosis (P = 0.017, HR = 1.655, CI = 1.093–2.505), vascular invasion (P = 0.001, HR = 2.200, CI = 1.392–3.476), and a high AGR2 level (P = 0.015, HR = 1.945, CI = 1.138–3.324) were independently associated with OS." (PMID 36899352, 2023). "Multivariate analysis showed that cirrhosis (P = 0.023, HR = 1.600, CI = 1.067–2.401), vascular invasion (P = 0.005, HR = 1.825, CI = 1.198–2.780), and a high AGR2 level (P = 0.043, HR = 1.662, CI = 1.017–2.716) were independently associated with RFS." (PMID 36899352, 2023). "Univariate analysis showed that cirrhosis (P = 0.022), AFP level (P = 0.033), vascular invasion (P = 0.003), AJCC stage (P = 0.003), and a high AGR2 level (P = 0.047) were significant predictors of worse RFS." (PMID 36899352, 2023). "For OS, univariate analysis showed that cirrhosis (P = 0.020), AFP level (P = 0.012), vascular invasion (P < 0.001), AJCC stage (P = 0.007), and a high AGR2 level (P = 0.018) were significant predictors of worse OS." (PMID 36899352, 2023). "Multivariate analysis showed that cirrhosis (P = 0.034, HR = 4.563, CI = 1.122–18.555), BCLC stage (P < 0.001, HR = 2.928, CI = 1.908–4.494), and a high AGR2 level (P = 0.008, HR = 1.735, CI = 1.154–2.609) were independently associated with OS." (PMID 36899352, 2023). "For OS, univariate analysis showed that cirrhosis (P = 0.023), AFP level (P = 0.011), tumor size (P = 0.001), CLIP score (P < 0.001), BCLC stage (P < 0.001), AJCC stage (P < 0.001), and a high AGR2 level (P = 0.002) were significant predictors of worse OS." (PMID 36899352, 2023).
colorectal adenocarcinoma (1 paper, 2024). The most common type of colorectal carcinoma. "We confirmed a significant correlation in mRNA levels between AGR2 and CD274 in the GDAC Firehose dataset (previously known as TCGA provisional) as well as in Colorectal Adenocarcinoma TCGA PanCancer Atlas consisting of 526 samples/patients." (PMID 39300184, 2024).
cystic fibrosis (1 paper, 2025). Autosomal recessive disorder caused by pathogenic variants in the CFTR gene (cystic fibrosis transmembrane conductance regulator), which encodes a chloride and bicarbonate channel expressed in epithelial cells, and follow the diagnosis criteria. "Additionally, biallelic AGR2 mutations cause a clinical disorder that mimics cystic fibrosis, characterized by decreased production of components of the mucociliary machinery." (PMID 40867591, 2025). "Since AGR2 is required for proper formation of the mucociliary machinery, and AGR3 is required for calcium-mediated regulation of ciliary function, double AGR2/AGR3 knockout may exhibit severe lung phenotypes resembling those seen in cystic fibrosis." (PMID 40867591, 2025).
endometrial adenocarcinoma (1 paper, 2018). "All 4 steroid receptors were expressed only in ISK cells that was established from a well-differentiated Grade-1 human endometrial adenocarcinoma representing LGEC in our cohort, therefore, was chosen to ascertain the effect of estrogen and androgen on the AGR2 transcription." (PMID 30140383, 2018).
fibrolamellar carcinomas (1 paper, 2019). "In examining the AGR2 expression in PDAC-related tissues using tissue microarrays, six out of eight fibrolamellar carcinomas samples and three out of four metastatic fibrolamellar carcinomas samples had a high expression." (PMID 31247903, 2019).
gastro-esophageal reflux (1 paper, 2011). "The results support the deduction that BE is a tissue with enhanced glycoprotein synthesis machinery (DPP4, ATP2A3, AGR2) designed to provide strong mucosal defenses aimed at resisting gastro-esophageal reflux." (PMID 21829465, 2011).
glioma (1 paper, 2025). A benign or malignant brain and spinal cord tumor that arises from glial cells (astrocytes, oligodendrocytes, ependymal cells). "AGR2’s co-expression with stemness markers such as Nestin and Vimentin highlights its role in maintaining glioma stem cell survival and contributing to recurrence, positioning AGR2 as a potential diagnostic and therapeutic target." (PMID 41179304, 2025).
hypopharyngeal cancers (1 paper, 2022). Carcinoma, predominantly squamous cell, arising from the epithelial cells of the hypopharynx. "Herein, we newly demonstrated that 4 genes (and the proteins) as the most powerful exploratory markers for response prediction to TXT, CDDP, and 5-FU- namely, AGR2, and PDE4D for TXT; NINJ2 and possibly RAB15 for CDDP, and CDC25B for 5-FU- in hypopharyngeal cancers." (PMID 35841085, 2022).
influenza infection (1 paper, 2022). "We found that in Pou2f3-/-, Trpm5-/-, and Il4ra-/- animals, the percent of Agr2+ area within Krt5+ area was not significantly different from controls following influenza infection." (PMID 36073526, 2022).
intestinal infection (1 paper, 2011). "Although the actual function of the gene is not known, it has been shown that mice lacking a functional copy of AGR2 show increased susceptibility to intestinal infection." (PMID 21698235, 2011).
large cell carcinoma (1 paper, 2015). A malignant epithelial neoplasm composed of large, atypical cells. "Although in all NSCLC, AGR2 expression appeared to be inversely correlated to grade (P = 0.004), the major contributor was the lower expression in grade 4 tumors (large cell carcinomas)." (PMID 26445321, 2015).
metastasis (1 paper, 2025). The spread or migration of cancer cells from one part of the body (where they first appeared) to another. "Furthermore, the positive detection rates of MACC1 and AGR2 exhibited a positive correlation with tumor grade, tumor-node metastasis classification, and lymph node metastasis (LNM) stage, while demonstrating a negative correlation with OS." (PMID 41239615, 2025).
mucinous lung adenocarcinomas (1 paper, 2017). "Thus, FOXM1 is essential for AGR2 expression and the mucinous phenotype in human mucinous lung adenocarcinoma cell lines." (PMID 29267283, 2017). "Thus, FOXM1 induces AGR2 in mouse and human mucinous lung adenocarcinomas." (PMID 29267283, 2017).
pancreatic diseases (1 paper, 2010). "The level of AGR2 in pancreatic juice was significantly higher in patients with pre-malignant pancreatic diseases compared to benign disease controls (p = 0.003)." (PMID 20550709, 2010).
Pleural effusion (1 paper, 2025). The presence of an excessive amount of fluid in the pleural cavity. "In liver metastasis BL T cells, granzyme family genes (GZMA, GZMH, and GNLY) were enriched, while pleural effusion BL T cells showed increased TFF3, AGR2, MGP, and MIF expression." (PMID 39955556, 2025).
prostate neuroendocrine small cell carcinoma (1 paper, 2016). "These antibodies detected AGR2 expression in prostate neuroendocrine small cell carcinoma, which was shown by our monoclonal antibodies and DNA arrays to be negative for AGR2." (PMID 26894971, 2016).
serous carcinoma (1 paper, 2018). "The absence of the AGR2 protein was observed in high‐grade serous carcinoma (P < .001) and significantly associated with disease‐free survival (DFS; P = .034)." (PMID 29845750, 2018). "The absence of the AGR2 protein was observed differentially expressed in high‐grade serous carcinoma (<0.001), samples with lymphatic vascular invasion (P = .003), bilateral involvement (P = 0.005) necrosis (P = .034), ovarian surface involvement (P = .032), and lymph node metastasis (P = .003)." (PMID 29845750, 2018).
teratoma (1 paper, 2024). A non-seminomatous germ cell tumor characterized by the presence of various tissues which correspond to the different germinal layers (endoderm, mesoderm, and ectoderm). "Secondly, it paves the way for the development of targeted therapies specifically aimed at teratoma, exploiting the unique vulnerabilities exposed by AGR2 and KRT19 overexpression." (PMID 38396829, 2024). "This robust validation step underscored the potential of AGR2 and KRT19 as reliable biomarkers for differentiating teratoma from necrosis in clinical practice." (PMID 38396829, 2024).
thyroidal neoplasms (1 paper, 2024). "The most striking diagnostic aspect for AGR2 was its significant upregulation in a large number of thyroidal neoplasms." (PMID 39533806, 2024). "In summary, our data provide a comprehensive overview of AGR2 expression in different tumor entities, identify AGR2 IHC as a potential diagnostic aid for the identification of thyroidal neoplasms, and demonstrate a potential prognostic role of AGR2 in various cancer types." (PMID 39533806, 2024). "It is concluded that AGR2 expression occurs in a broad range of different tumor entities and that AGR2 assessment may serve as a diagnostic aid for the distinction of thyroidal neoplasms and as a prognostic marker in various cancer types." (PMID 39533806, 2024).
tumor (176 papers, 2003 to 2026). "AGR2 is predominantly expressed in CD163+ M2-like tumor-associated macrophages (TAMs), with levels rising alongside tumor stage." (PMID 41836390, 2026). "This variant preserves its affinity for AGR2 and retains its anti-tumor efficacy against SKOV-3 ovarian cancer xenografts in nude mice." (PMID 40867591, 2025). "Comparable findings have been documented in other research, underscoring the close association between AGR2 overexpression and tumor progression as well as metastasis." (PMID 41239615, 2025). "The emergence of drug resistance within tumor cells significantly undermines treatment efficacy, with AGR2 implicated in promoting cancer progression and fostering drug resistance." (PMID 39062458, 2024). "Relying on the results from SWATH MS and subsequent immunochemical validation, we selected NMP3 as the top candidate protein associated with AGR2 in CRC tumour cells in our screen." (PMID 39300184, 2024). "AGR2 dysregulation has been linked to a range of diseases, including inflammatory bowel diseases, neoplasm development, and cancer progression." (PMID 38822246, 2024). "AGR2 has also been found to be a prominent pro-tumorigenic gene that has consistently been associated with tumour onset and progression in a number of cancer types, including CRC." (PMID 39348343, 2024). "Elevated AGR2 expression was associated with unfavorable tumor features in only one of our cancer entities." (PMID 39533806, 2024). "Again, it cannot be excluded that AGR2 neo‐expression in tumors derived from non‐AGR2‐expressing normal cells is caused by random alterations occurring because of tumor cell dedifferentiation." (PMID 39533806, 2024). "The expression of AGR2 in the TME has been associated with the infiltration of tumor immune cells (such as memory B cells, CD8+ T cells) and better prognosis." (PMID 39062458, 2024). "The results showed that increased tumor AGR2 mRNA expression was associated with decreased disease specific survival (DSS) among 1341 women (P = 0.03)." (PMID 37197416, 2023). "AGR2 expression is also mainly restricted to epithelial cells, and is associated with cancer cell proliferation, survival and tumor growth, as well as invasion and metastasis." (PMID 36329620, 2023). "Increased expression of known EAC-associated genes such as MUC1 and AGR2 was observed within the tumour." (PMID 36253784, 2022). "With therapies targeting inhibition of AGR2, tumor cells are more susceptible to proteotoxic stress, which helps prevent tumor metastasis and slow its spread." (PMID 35804819, 2022). "In order to distinguish germline polymorphisms from potential mutations in tumour tissues, we first listed the AGR2 and AGR3 gene polymorphisms identified in the NCBI dbSNP database." (PMID 35857928, 2022). "In clinical samples as well as in CCLE cancer cell lines, the presence of oncogenic mutations and CNVs in various driver genes is associated with variations in AGR2/3 expression, depending both on the cancer gene and the tumour type." (PMID 35857928, 2022). "More importantly, AGR2 is a unique tumor-associated antigen because cancer cells express the extracellular form eAGR2 (on the cell surface and secreted) while normal cells express the intracellular form iAGR2 (localized to the endoplasmic reticulum)." (PMID 34911496, 2021). "In metastasised tumour tissues (peritoneum) of these mice, aberrant DNA methylation at CpG sites in the AGR2 promoter region was reported, and associated to an aggressive cell phenotype (migration and invasion)." (PMID 34452625, 2021). "AGR2 has been shown to be overexpressed in a variety of human adenocarcinomas wherein AGR2 promotes tumor growth and survival and is associated with adverse clinical outcomes." (PMID 34679944, 2021). "The pro-angiogenic and pro-metastatic activity of AGR2 caused less response of tumor to bevacizumab treatment." (PMID 30647455, 2019).